SMC1A (structural maintenance of chromosomes 1A)
Diseases named in the same sentence as SMC1A in open-access papers (continued):
Sharing a sentence is not in itself a finding about the gene and the disease.
autism (3 papers, 2020 to 2025). Persistent deficits in social interaction and communication and interaction as well as a markedly restricted repertoire of activity and interest as well as repetitive patterns of behavior. "Still, all data point to a lower prevalence and decreased severity of ID in RAD21 patients compared to NIPBL and SMC1A groups: developmental milestones are more frequently attained, the cognitive level is estimated higher, and aggression and autism are less frequent." (PMID 32193685, 2020).
Cognitive impairment (3 papers, 2024 to 2025). Abnormal cognition is characterized by deficits in thinking, reasoning, or remembering. "The cognitive impairment observed is generally more severe than in patients with mutations in the SMC1A, SMC3, BRD4, and RAD21 genes." (PMID 38673696, 2024). "Variants in the SMC1A gene are associated with a relatively mild clinical presentation, characterized by the absence of major structural abnormalities commonly seen in CdLS, along with only a slight cognitive impairment." (PMID 41153413, 2025). "However, divergent patterns between our findings with prior investigations that highlighted greater cognitive deficit in those with NIPBL variants, may also reflect more limited developmental gains over time in these individuals compared to those with an SMC1A variant." (PMID 38462617, 2024).
developmental delay (3 papers, 2022 to 2024). "In brief, results from this study show significant but comparable developmental delays in early childhood between those with NIPBL vs SMC1A variants; however, those with NIPBL variants present with more severe behavioral challenges." (PMID 38462617, 2024). "Main findings generally suggest similar developmental delays in early communicative and motor development across those with a variant in either NIPBL and SMC1A, albeit those with NIPBL variants showed greater variability in the achievement of more complex language and motor milestones." (PMID 38462617, 2024).
epileptic encephalopathies (3 papers, 2023 to 2026). "The aim of the narrative review is to evaluate the genetic and clinical features of the SMC1A gene mutation with a comprehensive analysis of the role of SMC1A variants in developmental and epileptic encephalopathy." (PMID 41153413, 2025). "Germline mutations in SMC1A cause X-linked neurodevelopmental syndromes, most notably a milder variant of CdLS and epileptic encephalopathies in females." (PMID 41153413, 2025). "Studies show that XCI skewing correlates with clinical severity in female patients with early-onset epileptic encephalopathy due to SMC1A mutations." (PMID 41153413, 2025). "In many cases genotype–phenotype correlations remain incomplete, with closely located SMC1A variants associated either with CdLS-like features or with isolated epileptic encephalopathy." (PMID 41153413, 2025). "SMC1A is generally associated with CdLS and epileptic encephalopathy due to germline mutations." (PMID 41153413, 2025).
gastric cancer (3 papers, 2023 to 2025). A primary or metastatic malignant neoplasm involving the stomach. "For instance, BioPathNet’s path gradients clarify drug-disease associations, such as Bosutinib for ALL and Acitretin for gastric cancer, and highlight key paths and genes like SMC1A and POLA1 in Clofarabine’s mechanism." (PMID 39372928, 2024). "This reseach aims to explore the role and the underlying mechanisms of SMC1A in gastric cancer (GC)." (PMID 37537540, 2023). "SMC1A accelerates gastric cancer (GC) progression by upregulating SNAIL, thereby promoting EMT and enhancing cell proliferation, migration, and invasion." (PMID 40821814, 2025). "Our cell function and mechanism assays revealed that SMC1A facilitates gastric cancer cells proliferation, migration and invasion via promoting SNAIL activated EMT." (PMID 37537540, 2023). "Taken together, these results suggest that SMC1A promotes proliferation, migration, and invasion of gastric cancer cells." (PMID 37537540, 2023). "To investigate the characteristics in gastric cancer, we analysed SMC1A in the TCGA stomach adenocarcinoma database." (PMID 37537540, 2023). "We also assessed the expression of SMC1A mRNA and protein in human gastric cancer cell lines (AGS, HGC27 and NCI-N87) and the human gastric epithelial cell line GES-1." (PMID 37537540, 2023). "We further examined the expression of SMC1A in fresh tissue samples from 20 gastric cancer patients and found that SMC1A expression was higher in cancer tissues than that in corresponding adjacent tissues." (PMID 37537540, 2023). "Our study revealed that SMC1A promotes EMT process by upregulating SNAIL, which contributes to gastric cancer cell proliferation, migration and invasion." (PMID 37537540, 2023). "In summary, our study revealed SMC1A facilitates gastric cancer cell proliferation, migration and invasion via promoting SNAIL activated EMT, which indicated SMC1A may be a potential target for gastric cancer therapy." (PMID 37537540, 2023).
microcephaly (3 papers, 2020 to 2024). A congenital or acquired developmental disorder in which the circumference of the head is smaller than normal for the person's age and sex. "Individuals with SMC1A truncating variants may be small and have microcephaly, but they do not exhibit the typical features of CdLS." (PMID 38673696, 2024).
myelodysplastic syndrome (3 papers, 2019 to 2024). A clonal hematopoietic disorder characterized by dysplasia and ineffective hematopoiesis in one or more of the hematopoietic cell lines. "In myelodysplastic syndromes (MDS), a heterogeneous group of clonal hematopoietic disorders characterized by cytopenia, ineffective hematopoiesis and an increased risk of progression to AML, RAD21, STAG2, and SMC1A are the most frequently mutated genes (∼15%) and are associated with poor survival." (PMID 30873408, 2019).
Rett syndrome (3 papers, 2023 to 2025). A severe neurodevelopmental disorder affecting the central nervous system. "Variants in SMC1A make up about 5% of those with CdLS, largely presenting with the non-classic form, although there is a group of individuals with loss of function variants in SMC1A presenting with a Rett syndrome-like phenotype." (PMID 38462617, 2024).
Roberts Syndrome (3 papers, 2013 to 2021). "Additionally, mutations in three Cohesin subunits (SMC1α, SMC3, RAD21) and in one Cohesin-interacting protein (NIPBL) have been found causal for CdLS, whereas mutations in ESCO2 are responsible for Roberts syndrome/SC Phocomelia (OMIM# 269000)." (PMID 33263776, 2021).
Anxiety (2 papers, 2023 to 2024). Intense feelings of nervousness, tension, or panic often arise in response to interpersonal stresses. "In addition, these individuals were more likely than those with SMC1A variants to demonstrate self-injurious behaviors, and anxiety." (PMID 38462617, 2024). "Indeed, it has been reported that in mice heterozygous for a knockout of SMC3, which encodes the SMC1A partner and the core subunit of cohesin, altered neural gene expression during cortical synapse formation leads to defective synapse development and anxiety-related behavior." (PMID 37107610, 2023).
epileptic seizures (2 papers, 2020 to 2023). "Seizures are common in CdLS, in particular, when accompanied by SMC1A variants (Pavlidis, Cantalupo, Bianchi, Piccolo, & Pisani, 2014)." (PMID 32856424, 2020).
hepatocellular carcinoma (2 papers, 2023 to 2025). A malignant tumor that arises from hepatocytes. "In hepatocellular carcinoma, aberrant phosphorylation of SMC1A has been associated with enhanced cell proliferation and migration." (PMID 39851557, 2025). "In hepatocellular carcinoma, SMC1A is aberrantly phosphorylated at Serine 966, and its phosphorylation has been shown to promote cell proliferation and migration." (PMID 39851557, 2025). "Phosphorylated SMC1A has been shown to promote cell proliferation and migration in hepatocellular carcinoma." (PMID 39851557, 2025). "Moreover, SMC1A has shown to be aberrantly phosphorylated and involved in progression of hepatocellular carcinoma." (PMID 39851557, 2025).
triple-negative breast carcinoma (2 papers, 2013 to 2025). An invasive breast carcinoma which is negative for expression of estrogen receptor (ER), progesterone receptor (PR), and human epidermal growth factor receptor 2 (HER2). "Structural maintenance of chromosome-1A (SMC1A) is overexpressed in various malignancies including triple-negative breast cancer (TNBC)." (PMID 39851557, 2025).
viral infection (2 papers, 2013 to 2025). "Gene ontology classes of the predicted cellular targets of HPV16-miR-H1-1 suggest important roles in host cell interactions of HPV 16, such as the cell cycle process (CUL3, CYP26B1, MAP3K11, PBRM1, SMC1A), especially the M phase (CYP26B1, PBRM1, SMC1A), which is important for viral infection." (PMID 23936163, 2013).
bladder cancer (1 paper, 2023). "Functional validation of the dataset confirmed GATA3, SPT6, and the cohesin complex components SMC1A, and RAD21, as permissive upstream positive regulators of PPARG gene expression in luminal bladder cancer." (PMID 37250326, 2023).
breast tumors (1 paper, 2025). "It is noteworthy, that Bamacan, a homolog of SMC3 (a binding partner of SMC1A) is found in basement membranes and cardiomyocytes, as well as in exosomes secreted from the breast tumors." (PMID 39851557, 2025). "Comparison of SMC1A expression in breast tumor and normal tissues was performed by mining the integrated database utilizing RNAseq data." (PMID 39851557, 2025). "Overall, SMC1A is aberrantly phosphorylated in breast tumors as compared to normal or adjacent normal tissues." (PMID 39851557, 2025). "The data showed that SMC1A is significantly overexpressed in breast tumor tissues compared to normal samples (from non-cancerous patients and pediatric tissues)." (PMID 39851557, 2025).
CHARGE syndrome (1 paper, 2020). CHARGE syndrome is a multiple congenital anomaly syndrome characterized by the variable combination of multiple anomalies, mainly Coloboma; Choanal atresia/stenosis; Cranial nerve dysfunction; Characteristic ear anomalies (known as the major 4 C's). "In one case, Rubinstein–Taybi syndrome (#S40, SMC1A gene) and Charge syndrome were suggested as the first diagnosis for a H46 with a variant in the HDAC8 gene." (PMID 32033219, 2020).
cleft palate (1 paper, 2024). Cleft palate is a fissure type embryopathy that affects the soft and hard palate to varying degrees. "Cardiac defects were found in a small percentage of SMC1A (15%) and SMC3 (19%) cases, with a small percentage also having cleft palates (3–8%)." (PMID 38673696, 2024).
Constipation (1 paper, 2024). Infrequent or difficult evacuation of feces. "Constipation and GERD are more common in patients with variants in the NIPBL and SMC1A genes, visual impairment in NIPBL, SMC1A, and HDAC8, structural brain abnormalities in NIPBL, and sleep problems in NIPBL and SMC1A." (PMID 38673696, 2024).
coronary heart disease (1 paper, 2025). "ATP7A and PHKA1 are likely related to the cardiovascular system, EBP is associated with coronary heart disease and skeletal-related conditions, ZFX is known to be involved in animal size and ovarian failure, and SMC1A is implicated in premature ovarian failure." (PMID 39940742, 2025).
eosinophilic disorders (1 paper, 2025).
focal epilepsy (1 paper, 2021). A seizure caused by a localized disorder. "SMC1A (structural maintenance of chromosomes 1A): One patient with focal epilepsy, beginning within the first month, of life has been described." (PMID 33919646, 2021).
holoprosencephaly (1 paper, 2023). Holoprosencephaly (HPE) is a complex brain malformation resulting from incomplete cleavage of the prosencephalon, occurring between the 18th and 28th day of gestation, and affecting both the forebrain and face, which results in neurological manifestations and facial anomalies of variable severity. "Six of these SMC1A LOFs have even been linked to the most severe midline brain defect, holoprosencephaly (HPE)." (PMID 37107610, 2023).
KBG syndrome (1 paper, 2020). KBG syndrome is a rare condition characterized by a typical facial dysmorphism, macrodontia of the upper central incisors, skeletal (mainly costovertebral) anomalies and developmental delay. "In two cases (#N19 NIPBL gene; #S36, SMC1A gene), KBG syndrome was the first suggested as most the probable clinical diagnosis." (PMID 32033219, 2020). "Whereas for NIPBL and RAD21 patients, KBG syndrome was the second most common diagnosis (top-five rank), 54.5% (18/33) and 66,7% (2/3), Rubinstein–Taybi syndrome appeared most frequently in SMC1A and HDAC8 patients, 50.0% (4/8) and 80.0% (4/5), respectively." (PMID 32033219, 2020).
liver fibrosis (1 paper, 2026). "This study provides new insights and highlights the promising potential of the SMC1A/LAMC2/PI3K/Akt axis as a therapeutic target for liver fibrosis." (PMID 41737731, 2026).
osteoporosis (1 paper, 2024). A condition of reduced bone mass, with decreased cortical thickness and a decrease in the number and size of the trabeculae of cancellous bone (but normal chemical composition), resulting in increased fracture incidence. "Low TNSALP levels, increased PPi and PEA levels, rickets-like bone deformities, and osteoporosis are attested in HPP, but not in cohesinopathy disorders (associated with mutations in the SMC1A gene)." (PMID 39519277, 2024).
proteinopathy (1 paper, 2025). "To determine whether TDP-43 regulation of SMC1A occurs in other neuronal cell types affected by TDP-43 proteinopathy, we similarly evaluated SMC1A APA and protein expression in DIV38 iPSC-derived motor neurons (iPSC-MNs) in which TDP-43 was knocked down for 10 days." (PMID 40454469, 2025).
sarcoma (1 paper, 2020). A usually aggressive malignant neoplasm of the soft tissue or bone. "In particular, increased expression of SMC1A mRNA were found to be significantly associated with poor DFS (p<0.05) and OS (p<0.05) in all sarcoma patients." (PMID 33460400, 2020). "In the present study, we found that SMC1A was more highly expressed in sarcoma tissue than in normal tissue in the ONCOMINE and GEPIA datasets, which was confirmed by IHC." (PMID 33460400, 2020). "According to these results, SMC1A mRNA was significantly upregulated in sarcoma patients." (PMID 33460400, 2020). "In summary, SMC1A plays a vital role in the occurrence and progress of sarcoma." (PMID 33460400, 2020). "As suggested by the CCLE datasets, SMC1A was also highly expressed in human sarcoma cell lines." (PMID 33460400, 2020). "In the present study, the prognostic value of SMC1A was confirmed in sarcoma patients." (PMID 33460400, 2020). "According to the Cancer Cell Line Encyclopedia (CCLE), SMC1A, SMC2, SMC3, SMC4, SMC5 and SMC6 are also highly expressed in sarcoma cell lines." (PMID 33460400, 2020). "It was confirmed that the expression levels of SMC1A, SMC2, SMC3, SMC4, SMC5 and SMC6 in sarcoma were higher than in normal tissues." (PMID 33460400, 2020). "We concluded that SMC1A, SMC2, SMC3, SMC4, SMC5 and SMC6 were all highly expressed in sarcoma cell lines." (PMID 33460400, 2020). "Results of Gene Expression Profiling Interactive Analysis (GEPIA) indicated that high expression of SMC1A was significantly related to poor overall survival (OS) (p<0.05) and disease-free survival (DFS) in sarcoma (p<0.05)." (PMID 33460400, 2020). "Our results also suggest that SMC1A and SMC2 are potential therapeutic targets for sarcoma, while levels of transcripts of SMC3, SMC4, SMC5 and SMC6 are potential prognostic markers to improve the survival rate and prognostic accuracy of sarcoma." (PMID 33460400, 2020). "We found that increased expression of SMC1A, SMC2, SMC3, SMC4, SMC5 and SMC6 might play a significant role in sarcoma tumorigenesis." (PMID 33460400, 2020). "Therefore, high expression SMC1A and SMC2 is potentially prognostic for sarcoma." (PMID 33460400, 2020). "However, only the overexpression of SMC1A and SMC2 was related to the OS of sarcoma patients, whereas SMC3, SMC4, SMC5 and SMC6 had no significant impact on prognosis." (PMID 33460400, 2020).
synovial sarcoma (1 paper, 2020). "This revealed that SMC1A, SMC2, SMC3, SMC4, SMC5 and SMC6 proteins were all more highly expressed in the synovial sarcoma tissues than in corresponding normal tissues." (PMID 33460400, 2020).
teratoma (1 paper, 2022). A non-seminomatous germ cell tumor characterized by the presence of various tissues which correspond to the different germinal layers (endoderm, mesoderm, and ectoderm). "In our study, CARD11(caspase recruitment domain family member 11) (mutated in 18% intracranial teratomas), IRS1(insulin receptor substrate 1) (18%), PSMD11(16%), RELN(16%), RRAS2(16%), SMC1A(16%), SYNE1(16%) and ZFHX3(16%) were the tumor-related genes with the highest mutation rates in our cohort." (PMID 36457486, 2022).